TRIM33 (tripartite motif containing 33)
Description:
Acts as an E3 ubiquitin-protein ligase. Promotes SMAD4 ubiquitination, nuclear exclusion and degradation via the ubiquitin proteasome pathway. According to PubMed:16751102, does not promote a decrease in the level of endogenous SMAD4. May act as a transcriptional repressor. Inhibits the transcriptional response to TGF-beta/BMP signaling cascade. Plays a role in the control of cell proliferation. Its association with SMAD2 and SMAD3 stimulates erythroid differentiation of hematopoietic stem/progenitor (By similarity). Monoubiquitinates SMAD4 and acts as an inhibitor of SMAD4-dependent TGF-beta/BMP signaling cascade (Monoubiquitination of SMAD4 hampers its ability to form a stable complex with activated SMAD2/3 resulting in inhibition of TGF-beta/BMP signaling cascade).
Synonyms: KIAA1113; RFG7; TIF1G; TIF1GAMMA; FLJ11429; TIFGAMMA; TF1G; PTC7; DDH4; ECTO
Tractability: Small molecule: a structure with a bound ligand is known; a high-quality ligand is known. PROTAC: UniProt records ubiquitination sites on it; ubiquitination databases record sites on it; its protein half-life has been measured; a small molecule that binds it is known.
Target class: Epigenetic regulator; Bromodomain; Reader
Gene: Protein-coding gene on chromosome 1 (114,392,781 to 114,511,244, reverse strand). Ensembl gene ENSG00000197323.
Subcellular location: Nucleus
Subcellular location (Human Protein Atlas): Vesicles; Nucleoplasm
Pathways (Reactome):
Developmental Biology: Germ layer formation at gastrulation
Signal Transduction: Downregulation of SMAD2/3:SMAD4 transcriptional activity
Gene Ontology:
Molecular function: co-SMAD binding; protein binding; R-SMAD binding; ubiquitin-protein transferase activity; ubiquitin protein ligase activity; zinc ion binding
Biological process: negative regulation of BMP signaling pathway; protein ubiquitination; regulation of transforming growth factor beta receptor signaling pathway; negative regulation of DNA-templated transcription; negative regulation of transcription by RNA polymerase II
Cellular component: nucleus; chromatin; nucleoplasm
Genetic constraint (gnomAD): Loss-of-function variants: 11 observed, 79.21 expected, observed/expected ratio (o/e) 0.14, 90% interval 0.086 to 0.23. The synonymous counts are far from expectation, so gnomAD's model fits this gene poorly and the ratio says little. Missense variants: 726 observed, 959.08 expected, observed/expected ratio (o/e) 0.76, 90% interval 0.71 to 0.81. Synonymous variants: 457 observed, 365.69 expected, observed/expected ratio (o/e) 1.25, 90% interval 1.16 to 1.35.
Homologues: Orthologues: chimpanzee TRIM33 (99% identical), dog TRIM33 (98% identical), guinea pig TRIM33 (98% identical), macaque TRIM33 (97% identical), rat Trim33 (97% identical), pig TRIM33 (96% identical), mouse Trim33 (96% identical), rabbit TRIM33 (92% identical), tropical clawed frog trim33 (81% identical), zebrafish trim33 (60% identical). Paralogues in human: TRIM24 (46% identical), TRIM66 (27% identical), TRIM28 (24% identical), TRIM46 (12% identical), TRIM71 (12% identical), TRIM2 (12% identical), TRIM3 (12% identical), TRIM37 (11% identical), TRIM9 (11% identical), TRIM67 (10% identical), TRIM36 (10% identical), TRIM56 (10% identical), and 68 more.
Diseases named in the same sentence as TRIM33 in open-access papers:
TRIM33 is named in the same sentence as 157 diseases in open-access papers, as found by Europe PMC text mining. Sharing a sentence is not in itself a finding about the gene and the disease. The quoted sentences say what the papers report.
dermatomyositis (89 papers, 2013 to 2026). Dermatomyositis (DM) is a type of idiopathic inflammatory myopathy characterized by evocative skin lesions and symmetrical proximal muscle weakness. "Recently, anti-transcriptional intermediary factor 1-gamma (TIF1γ) /tripartite motif-containing protein 33 (TRIM33) antibodies have been detected in dermatomyositis patients with malignancies." (PMID 27756887, 2016). "Up to now, scholars only reported somatic variances of JAK2 and TIF1g (TRIM33) that may possibly correlate with dermatomyositis, but most of the studies were case reports or from malignancy-associated dermatomyositis." (PMID 40599779, 2025). "Since both FIR and TIF1γ/TRIM33 engage in Wnt-signaling pathway to suppress tumor progression, anti-FIRs antibodies could be helpful for the screening of dermatomyositis patients with malignancies as well as anti-TIF1γ/TRIM33 antibodies." (PMID 27756887, 2016).
myositis (80 papers, 2016 to 2026). "Of note, two dysregulated miRNAs characterized in the plasma exosomes of cancer-associated myositis (hsa-let-7f-5p and hsa-miR-143-3p) were also among the predicted interactors of TRIM33 mRNA according to this analysis." (PMID 38929849, 2024). "For example, genetic modifications including somatic mutations and loss of heterozygosity in the TRIM33 gene encoding TIF1γ have recently been reported in tumours in adults with cancer-associated myositis [13▪]." (PMID 31415030, 2019).
breast carcinoma (24 papers, 2014 to 2025). "However, another study reported that the expression of TRIM33 was increased in 35.9% of patients with breast cancer, and its expression was associated with younger age, estrogen receptor (ER) negativity, and tumor diameter >2 cm." (PMID 39389957, 2024). "TRIM33 has been proposed as a prognostic predictor in breast cancer, where TRIM33 levels were reduced in both breast tissue and circulating plasma of breast cancer patients compared to healthy controls, and reduced TRIM33 expression was associated with worse overall survival." (PMID 32731534, 2020). "In preclinical models of ER+ breast cancer, we found that TRIM33 plays a role(s) in the regulation of E2-driven signaling and growth, but the effects varied between cell lines and levels of response." (PMID 38473207, 2024). "We found that ER+ breast cancer cells with TRIM33 knockdown remained growth induced by E2 stimulation." (PMID 38473207, 2024). "A comparison of ER+ breast cancer cell lines showed that TRIM33 levels were highest in MCF-7; thus, MCF-7 cells were used to generate two stable shRNA knockdown polyclonal models (#5 and #6)." (PMID 38473207, 2024). "Despite its known role as an E3 ubiquitin ligase, TRIM33 increased the stability of endogenous ER in breast cancer cells." (PMID 38473207, 2024). "KAT6A promotes SMAD3 binding to oncogenic chromatin modifier TRIM24 and disrupts its interaction with the tumor suppressor TRIM33, which lead to the tumor cell metastasis in breast cancer." (PMID 35430805, 2022). "TRIM24 and TRIM33 bind to each other in breast cancer cells, but this interaction remains unchanged in response to the DNA intercalating agent adriamycin or 10 Gy irradiation." (PMID 32731534, 2020). "For example, mir-21 and TRIM33, which are both regulators involved in breast cancer, are located in an MCF7-specific cluster, whereas mir-194-2, mir-192 and MEN1 as leukemogenesis in a K562-specific cluster." (PMID 24357409, 2014). "In addition to its tumor-promoting function, the expression of TRIM33 was downregulated in non-small cell lung cancer, breast cancer, glioma, and renal clear cell carcinoma." (PMID 39389957, 2024). "In conjunction with TRIM33 being identified by all three interactomes, further support for investigating the role for TRIM33 in ER+ breast cancer comes from findings in prostate cancer cells where TRIM33 modulates the activity of another nuclear hormone receptor, the androgen receptor." (PMID 38473207, 2024). "TRIM33 has proposed roles as an oncogene or tumor suppressor in breast cancer." (PMID 38473207, 2024). "In addition, the overexpression of TRIM33 is related to poor prognosis in patients with breast cancer." (PMID 39389957, 2024). "For patients with ER+ breast cancer exhibiting high levels of TRIM33 and ER, TRIM33 inhibition may be considered a therapeutic opportunity to downregulate ER and prevent estrogen-independent tumor growth, as is observed upon resistance to aromatase inhibitor therapy." (PMID 38473207, 2024). "However, in another study, patients with high TRIM33 showed poorer progression-free survival, indicating that there may be a diverse role for TRIM33 in breast cancer." (PMID 32731534, 2020). "Comparing our findings of an ER interactome with those previously reported in ER+ breast cancer cells, only three ER interactors were common to all studies (NCOA3, NCOR2, and TRIM33)." (PMID 38473207, 2024). "Among them, TRIM33/TIF-1γ has been reported to act as a SUMO E3 ligase of the transcriptional regulator, SnoN1, regulating the epithelial–mesenchymal transition (EMT) in organoids that derived from human breast cancer cell lines MDA-MB-231 and MCF7, and murine mammary gland epithelia cells." (PMID 35408996, 2022).
lung carcinoma (19 papers, 2014 to 2025). "Vepafestinib also inhibited the growth of multiple lung cancer patient-derived cell lines harboring RET fusions with different N-terminal partners (CCDC6, KIF5B, TRIM33) and a RETC634W-mutation-positive MTC cell line." (PMID 37743366, 2023). "In a previous report, we detected 15 RET fusion transcripts in cells taken from a lung cancer patient and confirmed five RET fusion partners (KIF5B, CCDC6, TRIM33, NCOA4, and CUX1)." (PMID 27150058, 2016). "In contrast to 13 fusion partner genes of RET in thyroid carcinoma, only KIF5B-RET, CCDC6-RET, TRIM33-RET and NCOA4-RET have been reported in lung cancer, and KIF5B-RET is the most commonly identified gene fusion in NSCLCs to date." (PMID 25047660, 2014).
hepatocellular carcinoma (13 papers, 2012 to 2025). A malignant tumor that arises from hepatocytes. "In hepatocellular carcinoma, the CpG island of the TRIM33 promoter is hypermethylated, and its expression is decreased." (PMID 39389957, 2024). "Two TRIMs, TRIM24 and TRIM33, described in isolation in this review are known to form a complex that co-operatively acts in tumour suppression in hepatocellular cancer cells." (PMID 29110249, 2018). "Besides, studies have shown that TRIM33 can participate in the TGF-β signaling pathway by binding to phosphorylated SMAD2/3 or monoubiquitinated SMAD4 in hepatocellular carcinoma, human chronic myelomonocytic leukemia, and pancreatic cancer." (PMID 32908919, 2020). "An example of this is the upregulation of TRIM33 caused by the action of circSMAD2 and the following decreased expression of SMAD4, which blocks the TGF-β signaling pathway in HCC (hepatocellular carcinoma) cells." (PMID 41283360, 2025). "However, recent studies showed that loss of TRIM24 in mice led to hepatocellular carcinoma development and TRIM24 interacted with TRIM28 and TRIM33 to form regulatory complexes that suppressed murine hepatocellular carcinoma, suggesting its role as a tumor suppressor in heptocellular carcinoma." (PMID 22666376, 2012). "Moreover, the complex plays a role in tumor suppression, as simultaneous inactivation of TRIM24 and TRIM33 in mice leads to the development of hepatocellular carcinoma (HCC), highlighting their cooperative function in regulating cellular processes beyond viral infection." (PMID 40421416, 2025). "Furthermore, the downregulation of the E3 ubiquitin ligase tripartite motif-containing 33 (TRIM33) leads to the stabilization of TFRC through reduced ubi quitination, thereby inhibiting ferroptosis in hepatocellular carcinoma." (PMID 39624080, 2024). "Contrastingly, TRIM24 was reported to act as a tumour suppressor in murine hepatocellular carcinoma (HCC) by dysregulating retinoic acid receptor (RAR) signalling, and it was later shown that TRIM24, TRIM28 and TRIM33 can form regulatory complexes to suppress murine HCC." (PMID 32731534, 2020). "While the function of TRIM33 in cancer has not been fully elucidated, it has been identified as a tumour suppressor in several cancer types, including chronic myelomonocytic leukaemia (CMML) and hepatocellular cancer, where TRIM33 is downregulated through hypermethylation of its promoter region." (PMID 38627415, 2024).
non-small cell lung carcinoma (9 papers, 2017 to 2025). A group of at least three distinct histological types of lung cancer, including non-small cell squamous cell carcinoma, adenocarcinoma, and large cell carcinoma. "Somatic RET rearrangements (as fusion genes with CCDC6, NCOA4, KIF5B, PRKAR1A, TRIM33 and other rarer partners) have now been found in 1–2% of non-small-cell lung cancers (NSCLC) and at lower prevalence in many other cancers including pancreatic, colon, breast and salivary gland." (PMID 39655713, 2025). "In addition, TRIM33 was shown to be negatively regulated by HSPB5 in non-small-cell lung cancer cells (A549 cells)." (PMID 35333698, 2022).
pancreatic cancer (9 papers, 2009 to 2024). "Meanwhile, upon binding to Smad2/3, TRIM33 competes with Smad4 in pancreatic cancer, leading to a different effect from the classical complex." (PMID 39768197, 2024). "In vivo studies in mouse models with orthotopic pancreatic cancer demonstrated that TRIM33 suppressed tumor progression by modulating TGF-β signaling." (PMID 39768197, 2024). "Herein, we presented a case of a 68-year-old man with pancreatic cancer harboring TRIM33-RET fusion who responded remarkably to pralsetinib despite being intolerant to chemotherapy." (PMID 37139148, 2023). "While RET fusion is rare (0.6%) in pancreatic cancer, the efficacy of RET-targeted treatment in patients with TRIM33-RET fusion has not been previously reported." (PMID 37139148, 2023).
chronic myelomonocytic leukemia (8 papers, 2015 to 2024). A myelodysplastic/myeloproliferative neoplasm which is characterized by persistent monocytosis, absence of a Philadelphia chromosome and BCR/ABL fusion gene, fewer than 20 percent blasts in the bone marrow and blood, myelodysplasia, and absence of PDGFRA or PDGFRB rearrangement. "In addition, TRIM33 located at 1p13 region was identified as a tumor suppressor chronic myelomonocytic leukemia and associated with the survival of all B cell neoplasms." (PMID 34926267, 2021). "Moreover, TRIM33 also functions as a tumour suppressor in the haematological malignancies multiple myeloma (MM) and chronic myelomonocytic leukaemia (CMML)." (PMID 32731534, 2020). "However, we observe a modest expansion of myeloid cells upon short durations of TRIM33 suppression in vivo and Trim33−/− mice have been shown to develop chronic myelomonocytic leukemia." (PMID 25919951, 2015).
pulmonary fibrosis (8 papers, 2020 to 2025). Chronic progressive interstitial lung disorder characterized by the replacement of the lung tissue by connective tissue, leading to progressive dyspnea, respiratory failure, or right heart failure. "Consistently, hematopoietic-specific TRIM33 deficient mice exhibited an aggravated fibrotic progression, confirming the protective role of TRIM33 in pulmonary fibrosis, at least partly through the regulation of the TGF-β1 pathway in macrophages." (PMID 37681924, 2023). "Previous study has shown that HSPB5 can reduce the expression of Trim33 and affect the progression of pulmonary fibrosis." (PMID 35333698, 2022). "TRIM33 was overexpressed in alveolar macrophages and fibroblasts in idiopathic pulmonary fibrosis patients and fibrotic lungs of rodents." (PMID 36301038, 2022). "It is suggested that tripartite motif-containing 33 (TRIM33) alleviates pulmonary fibrosis via inhibition of TGF-β signaling pathway." (PMID 33381035, 2020). "Interestingly, previous studies have shown that upregulation of HSPB5 expression in idiopathic pulmonary fibrosis (IPF) can reduce the expression of TRIM33 and weaken the interaction between TRIM33 and Smad4, thus hindering the ubiquitination and nuclear output of Smad4." (PMID 35333698, 2022). "Conversely, depletion of TRIM33 leads to increased production of TGF-β1, inducing idiopathic pulmonary fibrosis (IPF) and interstitial lung inflammation through Smad4 and downstream inflammatory factors such as TNF-α and IL-6." (PMID 37415133, 2023). "TRIM33 gene knockout made mice sensitive to bleomycin (BLM)‐induced fibrosis, and AdCre‐TRIM33 inhibition aggravated BLM‐induced pulmonary fibrosis in mice." (PMID 36301038, 2022). "However, downregulation of TRIM33 promoted the TGF-β1 signaling pathway and aggravated lung fibrosis." (PMID 37923730, 2023). "The complex interactions between TRIM33, Smad4, and the small heat shock protein B5 (HSPB5) may represent key targets in the prevention of the progression of fibrosis in cases of induced lung fibrosis, as in iatrogenic diseases or in idiopathic pulmonary fibrosis." (PMID 37185726, 2023).
glioblastoma (7 papers, 2019 to 2024). The most malignant astrocytic tumor (WHO grade IV). "In human glioblastoma, it has been shown that TRIM33-mediated β-catenin destabilization is mediated through a dual effect." (PMID 32908919, 2020). "It should be pointed out that in glioblastoma, downregulation of TRIM33 has been shown to lead to the activation of the Wnt/β-catenin pathway, thereby promoting tumor cell proliferation and tumorigenesis." (PMID 32908919, 2020). "However, other studies have shown that TRIM33 can influence the occurrence and development of glioblastoma through the Wnt/β-catenin pathway." (PMID 32908919, 2020). "Furthermore, TRIM33 acts as a tumor suppressor by degrading CTNNB1 in human glioblastoma." (PMID 39062881, 2024).
prostate carcinoma (7 papers, 2021 to 2025). A carcinoma that arises from epithelial cells of the prostate gland. "TRIM33 has been implicated in the progression and prognosis of liver, pancreatic, lung, and prostate cancers acting in a context-dependent manner as an oncogene or tumor suppressor." (PMID 38473207, 2024). "TRIM33 was recently reported to have stabilizing effects on androgen receptors in prostate cancer cells by preventing Skp-2 mediated proteasomal degradation." (PMID 38473207, 2024). "In vitro and in vivo studies have confirmed that TRIM33 plays an important role in valproic acid inhibiting the migration and invasion of prostate cancer cells." (PMID 36301038, 2022). "In addition, TRIM33 significantly enhances AR transcriptional activity by preventing Skp2-mediated degradation of AR, thereby promoting prostate cancer growth." (PMID 39160596, 2024). "Moreover, two other TRIM proteins (TRIM33 and TRIM24) have been reported as oncogene or oncogenic transcriptional activators in B-cell leukemias and prostate cancer, respectively." (PMID 34284744, 2021).